SDHD (succinate dehydrogenase complex subunit D)
Diseases named in the same sentence as SDHD in open-access papers (continued):
Sharing a sentence is not in itself a finding about the gene and the disease.
Carney-Stratakis syndrome (6 papers, 2014 to 2025). Carney-Stratakis syndrome is a recently described familial syndrome characterized by gastrointestinal stromal tumors (GIST) and paragangliomas, often at multiple sites. "Based on a summary of reported Carney-Stratakis syndrome cases, we found that germline mutations in the SDHB and SDHD genes were the most common." (PMID 36387130, 2022). "Most of SDH mutations in GIST are germline, in particular germline mutations in SDHB, SDHC, and SDHD occur in about 20–30% of SDH-deficient disease and may be referred to as a Carney-Stratakis syndrome (CSS)." (PMID 35059314, 2021).
neuroblastoma (6 papers, 2004 to 2025). Neuroblastoma (NB) is the most common solid, extracranial childhood tumor. "SDHD mutations have been associated with cancers, including neuroblastoma." (PMID 40562609, 2025). "In this study, we investigated the possible involvement of SDHD in neuroblastoma (NB) tumourigenesis." (PMID 15331017, 2004). "In this study, we sought for evidence for involvement of SDHD in neuroblastoma." (PMID 15331017, 2004). "Studies have shown that the knockout of SDHD in human glioma SNB19 cells and human neuroblastoma SHSY5Y cells can reduce cell proliferation." (PMID 33101026, 2020). "Our study provides no indications for 2-hit involvement of SDHD in the pathogenesis of neuroblastoma." (PMID 15331017, 2004). "However, protein analyses and assessment of mitochondrial morphology presently do not provide clues as to the possible effect of reduced SDHD expression on the neuroblastoma tumour phenotype." (PMID 15331017, 2004). "Also, although a haplo-insufficient mechanism for SDHD involvement in advanced stage neuroblastoma could be considered, the present data do not provide consistent evidence for this hypothesis." (PMID 15331017, 2004).
multiple endocrine neoplasia type 2 (5 papers, 2006 to 2024). Multiple endocrine neoplasia type 2 (MEN2) is a multiple endocrine neoplasia, a polyglandular cancer syndrome characterized by the occurrence of medullary thyroid carcinoma (MTC), pheochromocytoma (PCC), in one variant, primary hyperparathyroidism (PHPT). "The whole-life incidence of PH and PGL is high in familial syndromes with these tumors: 1–5% in neurofibromatosis type 1 (NF1), 15–20% in VHL, 30–50% in multiple endocrine neoplasia type 2 (MEN-2), and probably more than 50% in SDHB and SDHD gene mutation carriers." (PMID 17156452, 2006).
renal carcinoma (5 papers, 2015 to 2025). A carcinoma arising from the epithelium of the renal parenchyma or the renal pelvis. "In addition, germline loss-of-function mutations of the TCA cycle enzyme genes, including FH, SDHB, SDHC, and SDHD, have been identified in renal cancers that appear to have an increased risk for more aggressive tumors." (PMID 34609963, 2021).
Cowden syndrome (4 papers, 2015 to 2025). "Mutations in the SDHB and SDHD genes have been reported to be associated with the so-called Cowden-2 syndrome (CS-2) and Cowden-3 syndrome (CS-3)." (PMID 36553592, 2022). "The SDHD:p.H102R mutation was previously submitted to ClinVar as a germline variant related to PPGLs, gastric stromal sarcoma, Cowden syndrome 3, and hereditary cancer-predisposing syndrome." (PMID 36614070, 2022). "Germline mutations in the PTEN tumor-suppressor gene and germline variations in succinate dehydrogenase subunit D gene (SDHD-G12S, SDHD-H50R) are associated with a subset of Cowden syndrome and Cowden syndrome-like individuals (CS/CSL) and confer high risk of breast, thyroid and other cancers." (PMID 25149476, 2015).
neuroendocrine tumors (4 papers, 2017 to 2025). "Long-term clinical follow-up include genetic background analysis such as SDHB, SDHD, VHL, and RET, required in view of the metastatic potential of this rare neuroendocrine tumor." (PMID 41426338, 2025).
pituitary adenomas (4 papers, 2015 to 2024). "They identified missense mutations in SDHB (c.487T>C, p.Ser163Pro) and SDHD (c.149A>G, p.His50Arg; c.53C>T, p.Ala18Val) among patients with sporadic pituitary adenomas." (PMID 39765842, 2024). "SDH subunit D (SDHD) mutation is found in an aggressive GH-secreting pituitary adenoma, indicating SDHD mutation might link to the progression of pituitary adenomas." (PMID 31649621, 2019). "Indeed, we have shown increased hypoxia inducible factor-1α in an SDHD-mutated case linked to pituitary adenoma." (PMID 25494863, 2015). "Similarly, mutations in the SDHD gene are frequently observed in invasive pituitary adenomas." (PMID 39765842, 2024).
Adrenal Pheochromocytoma (3 papers, 2010 to 2026). "Genetic disorders involving mutations within the succinate dehydrogenase B and D units (SDHB, SDHD) and the von Hippel-Lindau (VHL) gene places an increased risk in the development of extra-adrenal paragangliomas and adrenal pheochromocytomas, respectively." (PMID 21188160, 2010).
cardiomyopathy (3 papers, 2020 to 2022). A disease of the heart muscle or myocardium proper. "Subsequently an Irish male infant was described homozygous for a novel SDHD c.[275A > G];[275A > G];p.[(Asp92Gly)];[(Asp92Gly)] substitution, presenting with cardiomyopathy in utero." (PMID 34012134, 2021). "The two main phenotypes associated with Complex II-encoded genes, SDHA, SDHB, SDHD, and the assembly factor SDHAF1 are associated with progressive encephalopathy leukodystrophy, Leigh syndrome, and/or cardiomyopathy." (PMID 33426505, 2020).
colorectal cancer (3 papers, 2018 to 2023). A primary or metastatic malignant neoplasm that affects the colon or rectum. "Although the SDHD gene was not included in this study, it has previously been reported for its association with colorectal cancer." (PMID 33053772, 2020).
prostate carcinoma (3 papers, 2016 to 2022). A carcinoma that arises from epithelial cells of the prostate gland. "Similarly, increased succinate levels in prostatic cancer tissue accompanied with reduced SDHD expression were described as an important metabolic feature in a cohort of prostate cancer patients." (PMID 36551845, 2022).
thyroid cancer (3 papers, 2015 to 2019). "In this study, therefore, we sought to address our hypothesis that CS/CSL-associated germline variants in SDHD could alter PTEN nuclear localization through SRC-induced PTEN oxidation in thyroid cancer cells." (PMID 25149476, 2015). "Meanwhile, in sporadic thyroid cancers, about 6% of patients showed germline mutation of SDHB or SDHD." (PMID 31817761, 2019). "Indeed, we showed that more oxidized PTEN accumulates in the nuclei of SDHD-G12S and -H50R transfected thyroid cancer cells upon oxidative stress." (PMID 25149476, 2015). "However, very little is known about the underlying crosstalk between SDHD and PTEN in CS-associated thyroid cancer." (PMID 25149476, 2015). "Here, we show that two SDHD variants SDHD-G12S and SDHD-H50R as well as SDHD knockdown lead to more oxidized PTEN and increased nuclear PTEN accumulation under peroxide-induced oxidative stress, which consequently induced resistance to apoptosis and increased migration in thyroid cancer cells." (PMID 25149476, 2015). "Our current observations consistently show that SDHD-G12S and SDHD-H50R, as well as SDHD knockdown, lead to functional insufficiency of SDH and increased stability of HIF-1α in thyroid cancer cell lines." (PMID 25149476, 2015). "We show that SRC inhibition could rescue SDHD dysfunction-induced cellular phenotype and tumorigenesis only when wild-type PTEN is expressed, in thyroid cancer lines." (PMID 25149476, 2015).
cutaneous melanoma (2 papers, 2015 to 2017). A primary melanoma arising from atypical melanocytes in the skin. "Summary of the statistical associations between SDHD expression and the clinico-pathological parameters of cutaneous melanomas." (PMID 28662141, 2017). "The advanced clinico-pathological and patient survival association with SDHD mutation and/or expression in cutaneous melanoma remains controversial." (PMID 28662141, 2017). "SDHD promoter mutations were reported in 4–10% of cutaneous melanomas." (PMID 28662141, 2017). "The majority of ETS binding site altering SDHD promoter mutations (9 of 16 = 56%) were identified in the non-acral cutaneous melanoma." (PMID 26327518, 2015).
differentiated thyroid carcinoma (2 papers, 2015). Differentiated thyroid carcinoma (DTC), also known as papillary or follicular thyroid carcinoma, is a slow-growing malignancy usually presenting in adults as an asymptomatic thyroid mass. "When our pilot of 48 apparently sporadic DTC samples revealed germline variation in SDHB and SDHD, we expanded our series to a total of 241 unrelated PTEN mutation negative research participants with differentiated thyroid carcinoma from The Ohio State University's (OSU) Thyroid Center." (PMID 25694510, 2015).
encephalomyopathy (2 papers, 2018 to 2022). "Mutations in the gene for another succinate dehydrogenase subunit (SDHD) are also a cause of encephalomyopathy." (PMID 30478029, 2018).
essential hypertension (2 papers, 2021 to 2023). Hypertension that presents without an identifiable cause. "In a case from Turkey, an 81-year-old female was reported with multinodular goiter and essential hypertension had NM_003002.3:c.325C>T (Gln109Term) pathogenic variant in SDHD gene." (PMID 33777662, 2021).
gastric cancer (2 papers, 2004 to 2015). A primary or metastatic malignant neoplasm involving the stomach. "Subsequently, the reduced protein expression and loss of heterozygosity of SDHD gene have been identified in colorectal and gastric cancers." (PMID 25894340, 2015). "A similar correlation between 11q LOH and reduced SDHD expression was recently described in colorectal and gastric cancer." (PMID 15331017, 2004).
hypertrophic cardiomyopathy (2 papers, 2022 to 2023). A condition in which the myocardium is hypertrophied without an obvious cause. "Only two individuals (2/309) had P/LP variants in multiple genes: one harbouring predisposition to familial hypercholesterolemia (FH) and long QT syndromes (PCSK9, KCNH2) and the other with predisposition to cancer and hypertrophic cardiomyopathy (SDHD, MYBPC3)." (PMID 36335097, 2022). "This includes, on the rarer end of the phenotypic spectrum, hypertrophic cardiomyopathy, which is observed in individuals with biallelic variants in DLD, SDHA, SDHB, and SDHD." (PMID 38031187, 2023).
Lynch syndrome (2 papers, 2016 to 2020). An autosomal dominant hereditary neoplastic syndrome characterized by the development of colorectal carcinoma and a high risk of developing endometrial carcinoma, gastric carcinoma, ovarian carcinoma, renal pelvis carcinoma, and small intestinal carcinoma. "Four patients (36%) had a germline mutation; two had paraganglioma syndrome type 4 (SDHB), one had a paraganglioma syndrome type 1 (SDHD), and one had Lynch syndrome (PMS2)." (PMID 32824391, 2020).
ovarian carcinoma (2 papers, 2023 to 2025). A malignant neoplasm originating from the surface ovarian epithelium. "Dysregulation of SDHD sensitizes cyclin E-driven ovarian cancers to CDK inhibition." (PMID 41419500, 2025).
pheochromocytoma and paraganglioma (2 papers, 2017 to 2021). "The majority of hereditary pheochromocytoma and paraganglioma (PPGL) is caused by germline mutations in the SDHB, SDHC, or SDHD genes, which encode three (SDHB, SDHC, SDHD) of five subunits of succinate dehydrogenase (SDH) enzyme (SDHA, SDHDB, SDHC, SDHD, SDHAF2)." (PMID 34356532, 2021).
sarcoma (2 papers, 2020 to 2021). A usually aggressive malignant neoplasm of the soft tissue or bone.
thyroid tumor (2 papers, 2015 to 2023). A benign or malignant neoplasm affecting the thyroid gland. "Compared with available normal thyroid tissues (n=57), thyroid tumor tissue (n=484) showed significant reduction in PTEN, SDHC, and SDHD gene expression (P<0.001)." (PMID 25694510, 2015).
-deficient (1 paper, 2018). "Succinate dehydrogenase-deficient RCC is rare and results from inherited germline mutations in the succinate dehydrogenase (SDH) gene, most commonly SDHB but also in SDHA, SDHC and SDHD." (PMID 30123932, 2018).
adenoma (1 paper, 2021). A neoplasm arising from the epithelium. "A 24-year-old female in the current study was diagnosed with right surrenal adenoma with a novel pathogenic variant NM_003002.4:c.326A>G on SDHD gene (Case 18)." (PMID 33777662, 2021).
carotid body tumours (1 paper, 2015). "Patients with SDHC mutations are more likely to develop carotid body tumours, less likely to have multiple tumours than in SDHD mutated PGL, and have low malignant potential compared to SDHB-mutated PGL." (PMID 26273102, 2015).
cervical cancer (1 paper, 2024). A primary or metastatic malignant neoplasm involving the cervix. "In conclusion, our data demonstrated a clear association between Th17 levels as well as reduced SDHD expression and cervical cancer recurrence." (PMID 37899663, 2024). "Notably, patients with lymph node metastases exhibited high serum levels of succinate and in situ analysis revealed a correlation between numbers of Th17 cells and reduced SDHD expression that was associated with cervical cancer relapse." (PMID 37899663, 2024). "In line with this, our knock down of SDHC or SDHD in cervical cancer cells increased the expression of vimentin, ZEB1 and TWIST, but reduced e‐cadherin." (PMID 37899663, 2024). "To investigate the relationship between Th17 cells and SDH expression in cervical cancer patients, we analyzed SDHD expression by IHC in 52 clinical biopsies." (PMID 37899663, 2024). "Next, we analyzed the impact of Th17 cells on the expression of SDHC and SDHD in cervical cancer cells." (PMID 37899663, 2024). "To analyze the relevance of SDHC and SDHD for migration of cervical cancer cells we knocked down SDHC or SDHD with two specific siRNAs in three cervical cancer cells." (PMID 37899663, 2024). "Thus, our results indicated a functional link between Th17 cells and reduced SDHD expression during cervical cancer progression in vivo." (PMID 37899663, 2024). "Moreover, retrospective analysis demonstrated that in patients developing recurrence of cervical cancers SDHD expression was significantly less frequent in their tumor tissues than in patients without relapse." (PMID 37899663, 2024). "In summary, we could show that Th17 cells reduced the expression of SDHC and SDHD as well as activity of the SDH complex in cervical cancer cells." (PMID 37899663, 2024). "In our study, we identified that Th17 cells decreased the expression of SDHC and SDHD in cervical cancer cells resulting in diminished SDH complex activity that was mediated by miR‐142‐5p and validated SDHC and SDHD as new targets of miR‐142‐5p." (PMID 37899663, 2024). "Taken together, our data clearly showed that Th17‐induced enhanced migration and invasion of cervical cancer cells is dependent on miR‐142‐5p‐mediated suppression of SDHC and SDHD." (PMID 37899663, 2024). "Our data provide evidence that Th17 cells induced the expression of miR‐142‐5p in cervical cancer cells and identified SDHC and SDHD as new targets of miR‐142‐5p responsible for enhanced migration and invasion." (PMID 37899663, 2024). "12/52 were negative for SDHD expression in cervical cancer cells exhibiting partial stromal SDHD expression." (PMID 37899663, 2024). "IL‐17 expression was not solely found in T cells in cervical cancers; however, our analysis revealed that numbers of IL‐17‐expressing CD4 negative cells are not linked to SDHD expression in cervical cancers." (PMID 37899663, 2024). "We found a decline in SDHD expression during cervical cancer progression based on tumor FIGO stages resulting in a weak or absent SDHD expression in more advanced cervical cancers (r = −0.6228; P < 0.0001)." (PMID 37899663, 2024). "To investigate how miR‐142‐5p contributes to enhanced migration and invasiveness of cervical cancer cells we performed an in‐silico target prediction that identified subunits of the succinate dehydrogenase (SDH) complex with miR‐142‐5p binding sites in their 3′UTRs including SDHC and SDHD." (PMID 37899663, 2024).
colon cancer (1 paper, 2023). "According to the PDC database, compared with normal tissues, SDHA (p < 2.2×10-16), SDHB (p = 1.1×10-13), SDHC (p = 1.2 ×10-10), and SDHD (p = 0.00028) were low expressed in colon cancer at protein level." (PMID 36949947, 2023).
depression (1 paper, 2023). "SDHD and FERMT3 were found to be significantly associated with depression, and were identified as diagnostic and therapeutic signatures by our stroke cohorts with and without PSD, which could be a valuable reference for future clinical practice." (PMID 36968495, 2023). "SDHD and FERMT3 presented higher expression in the PSD group than the non-PSD group, indicating their potential roles in diagnosis of depression in stroke patients." (PMID 36968495, 2023). "Based on GSEA analysis of two signature genes (SDHD and FERMT3), we found that they have a significant correlation with depression." (PMID 36968495, 2023).
diabetic cardiomyopathy (1 paper, 2025). Diabetic cardiomyopathy is a disorder of the heart muscle in people with diabetes. "Notably, GSTK1 and UGT2B subfamily members co-regulate Chemical carcinogenesis-DNA adducts, Drug metabolism-Cytochrome P450, and extracellular exosome signaling, while IDH1/SDHB/SDHD link TCA cycle defects to redox imbalance in diabetic cardiomyopathy and tumorigenesis." (PMID 40626307, 2025).
esophageal squamous cell carcinoma (1 paper, 2022). Esophageal squamous cell carcinoma (ESCC) is a type of esophageal carcinoma (EC) that can affect any part of the esophagus, but is usually located in the upper or middle third. "Levodopa was shown to inhibit the proliferation of esophageal squamous cell carcinoma (ESCC) via down-regulating the levels of oxidative phosphorylation proteins which includes MT-CO3, SDHD and NDUFS4." (PMID 35392560, 2022).
follicular thyroid carcinoma (1 paper, 2015). "Here, we show SDHD-G12S and SDHD-H50R lead to impaired PTEN function through alteration of its subcellular localization accompanied by resistance to apoptosis and induction of migration in both papillary and follicular thyroid carcinoma cell lines." (PMID 25149476, 2015).
hereditary cancer (1 paper, 2020). Malignant neoplasms occurring in families at a rate greater than that expected by chance and caused by germline mutations in a specific gene. "Interestingly, despite the broad-based testing approach, pathogenic variants were only identified in the two most important SDH genes, namely SDHD and SDHB, with no pathogenic variants identified in any other PGL/PCC causative genes or other hereditary cancer genes." (PMID 33308260, 2020).
Immunodeficiency (1 paper, 2006). Failure of the immune system to protect the body adequately from infection, due to the absence or insufficiency of some component process or substance. "Underexpressed SDHD and CTNS are associated with immunodeficiency through curbed monocyte and CD4+ T cell -induced immunoregulation, respectively." (PMID 16956415, 2006).
intestinal tumor (1 paper, 2014). "QPCR, in an independent dataset, confirmed decreased expression (~50% of normal mucosal levels) of SDHD indicating a potential role for hypoxia in intestinal tumor biology." (PMID 25023465, 2014).
lung adenocarcinoma (1 paper, 2021). A carcinoma that arises from the lung and is characterized by the presence of malignant glandular epithelial cells. "miR-147b–mediated down-regulation of SDHD was reported to contribute to TCA cycle dysfunction in lung adenocarcinomas." (PMID 34878835, 2021).
lymph node metastases (1 paper, 2024). "Consistently, patients exhibited high levels of succinate in their serum associated with lymph node metastases and diminished expression of SDHD in patient biopsies correlated with increased numbers of Th17 cells." (PMID 37899663, 2024).